AKT1S1 (AKT1 substrate 1)
Description:
Negative regulator of the mechanistic target of rapamycin complex 1 (mTORC1), an evolutionarily conserved central nutrient sensor that stimulates anabolic reactions and macromolecule biosynthesis to promote cellular biomass generation and growth. In absence of insulin and nutrients, AKT1S1 associates with the mTORC1 complex and directly inhibits mTORC1 activity by blocking the MTOR substrate-recruitment site. In response to insulin and nutrients, AKT1S1 dissociates from mTORC1. Its activity is dependent on its phosphorylation state and binding to 14-3-3. May also play a role in nerve growth factor-mediated neuroprotection (By similarity).
Synonyms: PRAS40; MGC2865; Lobe
Tractability: Small molecule: a structure with a bound ligand is known; a high-quality ligand is known; it belongs to a druggable protein family. PROTAC: ubiquitination databases record sites on it; its protein half-life has been measured; a small molecule that binds it is known.
Gene: Protein-coding gene on chromosome 19 (49,869,033 to 49,879,470, reverse strand). Ensembl gene ENSG00000204673.
Subcellular location: Cytoplasm, cytosol
Subcellular location (Human Protein Atlas): Cytosol
Pathways (Reactome):
Signal Transduction: AKT phosphorylates targets in the cytosol; MTOR signalling; mTORC1-mediated signalling
Cellular responses to stimuli: HSF1-dependent transactivation
Disease: Constitutive Signaling by AKT1 E17K in Cancer
Gene Ontology:
Molecular function: protein binding; protein kinase inhibitor activity; protein serine/threonine kinase inhibitor activity
Biological process: negative regulation of cell size; negative regulation of protein kinase activity; negative regulation of TOR signaling; negative regulation of TORC1 signaling; regulation of apoptotic process; regulation of neuron apoptotic process; neurotrophin TRK receptor signaling pathway
Cellular component: cytosol; TORC1 complex; cytoplasm; nucleoplasm
Genetic constraint (gnomAD): Loss-of-function variants: 17 observed, 17.08 expected, observed/expected ratio (o/e) 1, 90% interval 0.68 to 1.49. The synonymous counts are far from expectation, so gnomAD's model fits this gene poorly and the ratio says little. Missense variants: 366 observed, 293.59 expected, observed/expected ratio (o/e) 1.25, 90% interval 1.14 to 1.36. Synonymous variants: 181 observed, 134.95 expected, observed/expected ratio (o/e) 1.34, 90% interval 1.19 to 1.52.
Homologues: Orthologues: chimpanzee AKT1S1 (99% identical), macaque AKT1S1 (99% identical), pig AKT1S1 (95% identical), mouse Akt1s1 (94% identical), rat Akt1s1 (93% identical), guinea pig AKT1S1 (92% identical), dog AKT1S1 (91% identical), tropical clawed frog akt1s1 (46% identical), zebrafish akt1s1 (33% identical), Drosophila melanogaster PRAS40 (24% identical).
Diseases named in the same sentence as AKT1S1 in open-access papers:
AKT1S1 is named in the same sentence as 85 diseases in open-access papers, as found by Europe PMC text mining. Sharing a sentence is not in itself a finding about the gene and the disease. The quoted sentences say what the papers report.
breast carcinoma (14 papers, 2010 to 2025). "The oncogenic roles of AKT1S1 have been reported in colon cancer, liver cancer, lung cancer, prostate cancer, breast cancer, and so on via regulating PI3K/Akt, mTOR, and/or NF-κB signaling pathways." (PMID 32656205, 2020). "Decreased phosphorylation of AKT1S1 at T246 was observed in all four breast cancer cell lines in response to GSK690693 treatment." (PMID 20604938, 2010).
gastric cancer (12 papers, 2017 to 2025). A primary or metastatic malignant neoplasm involving the stomach. "Meanwhile, circORC5 was shown to suppress gastric cancer progression by serving as a miR‐30c‐2‐3p sponge to regulate AKT1S1 expression." (PMID 37014625, 2023). "Our findings demonstrate that METTL14-mediated m6A modification of circORC5 suppresses gastric cancer progression by regulating miR-30c-2-3p/AKT1S1 axis." (PMID 35164771, 2022). "Previous studies have found that AKT1S1 is a direct target of miR-30c-2-3p in gastric cancer cells." (PMID 41169393, 2025). "A previous research has reported that METTL14 level was declined in the gastric cancer tissues, and METTL14-mediated m6A modification of circORC5 could inhibit the development of gastric cancer via regulating miR-30c-2-3p/AKT1S1." (PMID 38326804, 2024). "In gastric cancer, m6A modification of circORC5 repressed growth and invasion of GC cells progression by regulating miR-30c-2-3p/AKT1S1 axis." (PMID 36861189, 2023). "In gastric cancer, METTL14 was reported to be able to modulate the m6A modifications on circORC5 and thus abate the cell growth by the miR-30c-2-3p/AKT1 substrate 1 (AKT1S1) axis." (PMID 35804965, 2022). "In addition, circORC5 can absorb miR‐30c‐2‐3p, reverse the upregulation of miR‐30c‐2‐3p and downregulation of proline‐rich AKT1 substrate 1 (AKT1S1) and eukaryotic initiation factor 4B (EIF4B) induced by METTL14 and regulate the malignant progression of gastric cancer cells." (PMID 38263865, 2024).
Insulin resistance (7 papers, 2014 to 2024). Increased resistance towards insulin, that is, diminished effectiveness of insulin in reducing blood glucose levels. "For example, both FGF21 and AKT1S1 (also known as PRAS40) are substrates for phosphorylation by AKT kinase, and effect fatty liver disease, while IRF3 mediates HFD-induced insulin resistance and impaired hepatic glucose metabolism trough a mechanism involving AKT." (PMID 39060446, 2024). "In the case of IRS1 (cg21511036), AKT1S1 (cg03813033), ADCY2 (cg12566890 and EHMT2 (cg00210002) are hypomethylated, whereas AKT1 (cg01749142), FOXO3 (15283498), are hypermethylated in subjects with insulin resistance and hypertriglyceridemia." (PMID 30926763, 2019).
liver cancer (7 papers, 2017 to 2024). An epithelial or non-epithelial malignant neoplasm that arises from the liver. "In another investigation, it has been shown that PGK1 induced the phosphorylation of PRAS40 (the proline-rich AKT substrate of 40 kDa, encoded by the gene AKT1S1) at Thr246 in Ewing’s sarcoma cell line A673, and liver cancer cell lines HepG2 and SNU449." (PMID 37190124, 2023). "A high expression of AKT1S1 is positively correlated with a poor prognosis in liver cancer patients." (PMID 34671397, 2021).
hepatocellular carcinoma (6 papers, 2017 to 2025). A malignant tumor that arises from hepatocytes. "Moreover, AKT1S1 is upregulated in hepatocellular carcinoma and is associated with the poor prognosis of patients with hepatocellular carcinoma and promotes the growth of hepatocellular carcinoma." (PMID 41169393, 2025).
Ewing sarcoma (5 papers, 2020 to 2024). A small round cell tumor that lacks morphologic, immunohistochemical, and electron microscopic evidence of neuroectodermal differentiation. "AKT1S1, a substrate of protein kinase B (AKT1), encodes PRAS40 which was identified as a crucial downstream target of Ewing sarcoma protein (EWS), and previous studies revealed that PRAS40 is associated with the development of Ewing sarcoma." (PMID 34194501, 2021).
non-small cell lung carcinoma (4 papers, 2011 to 2020). A group of at least three distinct histological types of lung cancer, including non-small cell squamous cell carcinoma, adenocarcinoma, and large cell carcinoma. "Phosphorylation of at least two of the three further known Akt target proteins Proline-rich AKT1 substrate 1 (PRAS40), tuberous sclerosis 2 (TSC2) and TBC1 Domain Family Member 4 (TBC1D4) in non-small cell lung cancer cell lines also required Akt1-phosphorylation at T308 for their activation." (PMID 29562639, 2018).
diabetic nephropathy (3 papers, 2014 to 2016). "The reciprocal regulation of PTEN levels and AKT1 substrate 1 (PRAS40), a negative regulator of Tor complex 1 (TORC1) activity by miR-21, is shown to mediate critical pathologic features of diabetic kidney disease." (PMID 24550986, 2014). "Recent study on diabetic nephropathy shows that Smad7 and AKT1 substrate 1 (PRAS40), a negative regulator of Tor complex 1 (TORC1), are potential targets of miR-21." (PMID 25750628, 2015).
Obesity (3 papers, 2014 to 2022). Accumulation of substantial excess body fat. "Among all common DEGs, three genes (TNFRSF1B, CACNA1A, and AKT1S1) were found to be associated with obesity-related pathways from the Kyoto Encyclopedia of Genes and Genomes (KEGG) pathway database." (PMID 36499541, 2022). "Among URGTG, three genes, AKT1S1, TNFRSF1B, and CACNA1A, were found to be associated with obesity-related pathways (in KEGG database), which were thermogenesis (hsa04714), the adipocytokine signaling pathway (hsa04920), and type II diabetes mellitus (hsa04930), respectively." (PMID 36499541, 2022).
cyst (1 paper, 2024). A sac-like closed membranous structure that may be empty or contain fluid or amorphous material. "Compared with Akt1s1+/+Tsc2f/f; Cre mice, Akt1s1−/−Tsc2f/f; Cre mice exhibited smaller kidneys, lower ratios of kidney weight to body weight, fewer and smaller renal cysts, and lower cyst index." (PMID 39333852, 2024).
leukemia (1 paper, 2011). A malignant (clonal) hematologic disorder, involving hematopoietic stem cells and characterized by the presence of primitive or atypical myeloid or lymphoid cells in the bone marrow and the blood. "Interestingly, both of our studies detected novel CXCL12-responsive AKT substrates, PDCD4 (pS457) and AKT1S1 (pT246), underscoring the potential role of AKT signaling and leukemias." (PMID 21949786, 2011).
Renal cyst (1 paper, 2024). A fluid filled sac in the kidney. "To investigate the role of PRAS40 in TSC-associated renal cysts, we crossed Tsc2f/f; Cre mice with Akt1s1 globally deleted mice and obtained Akt1s1−/−Tsc2f/f; Cre mice." (PMID 39333852, 2024). "Akt1s1 deletion reduced the number of PCNA-positive cells in renal cyst epithelial cells." (PMID 39333852, 2024).
tumor (54 papers, 2011 to 2025). "The authors found that the suppression of miR-124 expression in the tumor led to increased expression of the AKT1S1 (AKT1 Substrate 1) gene encoding the enzyme PRAS40." (PMID 36362406, 2022). "Knockdown of METTL14 reduces the circORC5 m6A levels, increasing circORC5 expression and inhibiting tumor progression through the miR-30c-2-3p/AKT1 substrate 1 (AKT1S1) axis." (PMID 38856795, 2024). "PKM2 phosphorylated the mTORC1 inhibitor AKT1S1 and this facilitated the activation of mTORC1 signaling, leading to accelerated tumor growth." (PMID 37190033, 2023). "Accordingly, the protein expression of EIF4E3, RPTOR, and AKT1S1 were all significantly associated with the MGPS, suggesting the elevated RNA translation efficiency led by EIF4EBP1_pT37 could promote tumor cell proliferation." (PMID 36434634, 2022).
cancer (37 papers, 2011 to 2025). A tumor composed of atypical neoplastic, often pleomorphic cells that invade other tissues. "Among the genes most significantly correlated with LINC01134, we noted AKT1S1, which has been reported to be a critical oncogene in several cancers, including HCC." (PMID 32656205, 2020). "Importantly, we further noticed that AKT1S1 expression is also highly correlated to a worse NB patient outcome, as has been suggested for several other cancer types." (PMID 38255303, 2024). "AKT1S1 is a target of rapamycin, a drug used in the treatment of other cancers." (PMID 35626021, 2022). "Phosphorylation of S202/203 of AKT1S1 by PKM2 released AKT1S1 from raptor and facilitated its binding to 14-3-3, resulted in hormonal- and nutrient-signals independent activation of mTORC1 signaling and led accelerated oncogenic growth and autophagy inhibition in cancer cells." (PMID 26876154, 2016). "Phosphorylation of AKT1 substrate 1 (AKT1S1) at Ser202/203 by PKM2 facilitates its interaction with 14-3-3, triggering mTORC1 signaling and driving oncogenic growth in cancer cells." (PMID 40057191, 2025). "Several miRNAs regulate apoptosis in cancer cells with the involvement of MTORC1, which composed of mTOR, RPTOR, MLST8, and AKT1S1." (PMID 36835100, 2023). "PKM2 phosphorylates mTORC1 inhibitor AKT1 substrate 1 (AKT1S1) at Ser202/203, and PKM2-induced AKT1S1 phosphorylation promotes PKM2 binding to 14-3-3, activating mTORC1 signaling and accelerating oncogenic growth in cancer cells." (PMID 33292198, 2020).
gastrointestinal tract cancers (1 paper, 2021). "An upregulation of TGFBI was observed in gastrointestinal tract cancers and resulted in activation of the FAK/AKT/AKT1S1/PRS6/EIF4EBP pathway, playing a role in cell survival and proliferation." (PMID 33921897, 2021).
AKT1S1 also shares sentences with these, for which no sentence is quoted: glioma (10 papers); prostate carcinoma (10); melanoma (9); diabetes (6); infection (6); lung carcinoma (6); colon cancer (4); diabetic cardiomyopathy (4); glioblastoma (4); hyperlipidemia (3); metabolic disorders (3); renal carcinoma (3); sarcoma (3); (HCMV) infection (2); atherosclerosis (2); cervical cancer (2); colorectal cancer (2); head and neck squamous cell carcinoma (2); hyperglycaemia (2); intrahepatic cholangiocarcinoma (2); multiple myeloma (2); myocardial infarction (2); nervous system disorder (2); neuroblastoma (2); ovarian carcinoma (2); steatosis (2); Stroke (2); type 2 diabetes (2); Alzheimer disease (1); asthma (1).
A further 40 diseases each share a sentence with AKT1S1 in 1 paper.